RBM3 (RNA binding motif protein 3)
Diseases named in the same sentence as RBM3 in open-access papers (continued):
Sharing a sentence is not in itself a finding about the gene and the disease.
tumor (continued). "PFS was longer for patients with tumours displaying high nuclear or cytoplasmic RBM3 expression who received oxaliplatin based treatment as first-line chemotherapy, in comparison to irinotecan based treatment (p-value 0.020 for nuclear expression and 0.022 for cytoplasmic expression)." (PMID 28800641, 2017). "The difference in results between this study and ours may also be due to the fact that the most evident prognostic value of RBM3 expression seems to be for the NMI tumours." (PMID 28293425, 2017). "In patients with tumours displaying high RBM3 expression, we have also shown a significantly longer PFS in those treated with first-line oxaliplatin based chemotherapy compared to those treated with first-line irinotecan based chemotherapy, although the actual survival gain was less then one month." (PMID 28800641, 2017). "A few other studies have compared RBM3 expression in primary tumours and metastases." (PMID 28800641, 2017). "Since the effect of oxaliplatin appears to be limited in patients with tumours displaying low RBM3 expression, several patients could be spared suffering, at least temporarily, if another agent is given in first-line." (PMID 28800641, 2017). "However, the clinical data gathered on RBM3 in various tumor types with RBM3 as a marker of better outcome point toward a more complex network of RBM3 interaction than considered so far." (PMID 27147467, 2016). "One reason might be the fact that RBM3 facilitates mitosis and increases chemo sensitivity of tumor cells." (PMID 27147467, 2016). "For the optimal use of RBM3 in a prognostic model, other cut-off limits for plasma tumour markers may need to be applied." (PMID 25811459, 2015). "Furthermore, in a multivariable Cox regression model, including the prognostic factors used in the IGCCC model, low RBM3 expression was an independent predictor for treatment failure, when tumor markers (AFP, HCG and LDH) were entered as continuous variables." (PMID 25811459, 2015). "Our data suggest that RBM3 expression may provide additional prognostic information to that of tumor marker level and pattern of metastasis." (PMID 25811459, 2015). "Thus, the utility of RBM3 as a predictive marker for response to neoadjuvant chemotherapy merits further study, preferably in tumour samples from patients enrolled in randomized treatment trials." (PMID 24963396, 2014). "RBM3 expression was significantly reduced in more advanced tumour stages (p = 0.006)." (PMID 24963396, 2014). "Furthermore, RBM3 expression was significantly higher in primary tumours (p < 0.001) and metastases (p < 0.001) with a background of IM compared to cases without reported IM." (PMID 24963396, 2014). "Following antibody optimisation and staining, RBM3 expression could be evaluated in tumours from 343/344 (99,7%) cases." (PMID 23565664, 2013). "A similarly reduced, borderline significant, PFS was demonstrated for tumours with intermediate RBM3 expression, and when a dichotomised variable of high versus negative/intermediate RBM3 expression was applied, a significantly reduced PFS was seen for the latter category (p=0.048)." (PMID 23565664, 2013). "While the greatest impact on DSS and OS was seen for patients with tumours lacking RBM3 expression, an increased risk of disease progression was also observed in the patient group with intermediate expression." (PMID 23565664, 2013). "There was an inverse association between tumour diameter and RBM3 expression (p = 0.030) but not to depth of invasion (data not shown)." (PMID 21777469, 2011). "In addition, a markedly reduced expression of RBM3 was observed in metastases compared to primary tumours, which is quite in line with previous in vitro data." (PMID 21777469, 2011).
tumor (continued). "Multivariate analysis controlling for age, disease stage, differentiation grade and residual tumor volume confirmed that RBM3 expression was an independent predictor of RFS (HR = 0.61, 95% CI = 0.44-0.84, p = 0.003) and OS (HR = 0.62, 95% CI = 0.41-0.95; p = 0.028)." (PMID 20727170, 2010). "Moreover, RBM3 regulates post-transcriptional events such as mRNA stability and protein synthesis, processes that may suppress tumor aggressiveness or promote cellular differentiation." (PMID 40506997, 2025). "Hence, patients with high tumour-specific RBM3 expression who are considered unfit for cisplatin-based chemotherapy may have a benefit from gemcitabine." (PMID 35109796, 2022). "However, in xenografts models RBM3 downregulation reduces tumor growth and angiogenesis." (PMID 31440515, 2019). "Low RBM3 expression was an independent predictor of a reduced survival in the entire cohort (univariable HR 3.19; 95% CI 2.02–5.04, and multivariable HR 1.85; 95% CI 1.11–3.09), and in T1 tumours (univariable HR 2.64; 95% CI 1.11–6.27, and multivariable HR 2.63; 95% CI 1.01–6.84)." (PMID 28293425, 2017). "The possible mechanism proposed by the authors is that RBM3 in cancers involves in enhancing the balance between CD44v and CD44s expression to attenuate the stem cell like features to adapt to the change in the microenvironment for survival and repopulation of tumor cells." (PMID 28118608, 2017). "Therefore, we cannot draw any conclusions on the expression of RBM3 in the metastases, which may differ from the primary tumours." (PMID 28800641, 2017). "However, loss of RBM3 expression was found to be prognostic in all cases with radically resected primary tumours, with our without inclusion of the small number of cases having distant metastases." (PMID 24963396, 2014). "RBM3 expression could be evaluated in 173/175 (98.9%) primary tumours and 71/75 (94.7%) metastases." (PMID 24963396, 2014). "Moreover, in patients with Ta and T1 tumours, reduced RBM3 expression correlated with a significantly shorter time to disease progression, despite the comparatively low number of events, and negative RBM3 expression was an independent predictor of a reduced 5-year overall survival." (PMID 23565664, 2013). "RBM3 could be assessed in 215/226 (95.1%) of primary tumours and all metastases." (PMID 21777469, 2011). "Low RBM3 expression correlated with advanced tumor stage (III-IV), lymph node and distant metastasis, and larger tumor size." (PMID 41994650, 2026). "Members of the RBM family such as RBM3 and RBM47 display context-specific roles, acting as tumor suppressors in some settings and as oncogenic enhancers of Wnt in others." (PMID 41516083, 2025). "Accordingly, as compared with subcutaneous tumor cells, CTNNB1 mRNA was significantly up-regulated while RBM3 protein was significantly down-regulated in cancer cells growing in bone, which was consistent with our in vitro observations (see Result 2)." (PMID 36750551, 2023). "In contrast, silencing RBM3 decreased HCT116 colon adenocarcinoma cell proliferation and a complete shut down of tumor xenograft growth." (PMID 28118608, 2017). "Positive nuclear RBM3 expression was significantly more frequent in tumours located in the rectum, in BRAF wildtype tumours and in metachronous disease." (PMID 28800641, 2017). "The relevance of this finding, which may well be coincidental, is however less evident, as neither RBM3 expression in the metastases nor Ki67 expression in primary tumours or metastases were significantly associated with clinical outcome in the here analysed cohort." (PMID 24963396, 2014). "In this scenario, the response of cancer cells mediated largely by a group of stress-response proteins like RBM3 plays a crucial role in deciding the fate of cancer cells in the tumor microenvironment; that is “to be or not to be”." (PMID 36750551, 2023).
tumor (continued). "RBM3 overexpression impairs tumorigenesis in PC3 cells, it has demonstrated that in PC3-RBM3 cells the tumor volume was smaller or no tumor found compared with control PC3-GFP cells." (PMID 28118608, 2017). "In T2–T4 tumours, none of the established clinicopathological factors remained significant, but RBM3 was borderline prognostic in both univariable (HR 2.01, 95% CI 0.95–4.23) and multivariable analysis (HR 2.22, 95% CI 0.94–5.28)." (PMID 28293425, 2017). "After adding tumour type as a factor into the multivariable Cox regression analysis of the entire cohort, together with both PODXL and RBM3, RBM3 expression remained significant (HR 1.84, 95% CI 1.09–3.10, p = 0.022), but not PODXL expression (HR 1.43, 95% CI 0.77–2.67, p = 0.257)." (PMID 28293425, 2017). "A variety of human tumor specimens have been analyzed for CIRP and RBM3 expression." (PMID 27147467, 2016). "Inclusion of tumour location (esophagus, gastroesophageal junction and stomach) in the multivariable model did not alter the independent prognostic significance of RBM3 expression and tumour location per se was not prognostic (data not shown)." (PMID 24963396, 2014). "In patients with T1 tumours, a significant correlation was seen between negative RBM3 expression and a reduced 5-year OS in both univariable analysis (n=116; HR=2.44 95% CI 1.25-4.75) and multivariable analysis (HR=1.98 95% CI 1.01-3.90)." (PMID 23565664, 2013). "Kaplan-Meier analysis and log-rank test revealed a stepwise reduced DSS and 5-year OS with decreasing RBM3 expression, with the shortest DSS (p<0.001) and 5-year OS (p<0.001) for patients with tumours lacking RBM3 expression." (PMID 23565664, 2013). "Kaplan-Meier analysis using three categories of RBM3 expression revealed a significantly reduced PFS for patients with RBM3 negative tumours compared to tumours with high RBM3 expression (p=0.030)." (PMID 23565664, 2013). "Longitudinal analysis revealed that 16/31 (51.6%) of metastases lacked RBM3 expression, in contrast to the primary tumours in which RBM3 was absent in 3/215 (1.4%) cases and strongly expressed in 120/215 (55.8%) cases." (PMID 21777469, 2011). "RBM3 expression could be evaluated in 259/264 (98.1%) tumours, whereby negative RBM3 staining (NS = 0) was denoted in 26 (10.0%) cases, intermediate staining in 78 (30.1%) cases and strong staining in >75% of the cells in 155 (59.8%) cases." (PMID 28293425, 2017). "However, as RBM3 expression correlated with tumour stage and HCG level, RBM3 may also be related to inhibition of tumour growth and dissemination, through mechanisms still unknown." (PMID 25811459, 2015). "However, a significantly shorter 5-year OS was seen for RBM3 negative compared to RBM3 positive tumours in univariable analysis (n=231; HR=2.00 95% CI 1.21-3.33) and borderline significant in multivariable analysis (HR=1.64 95% CI 0.96-2.78)." (PMID 23565664, 2013). "In addition, as determined by comparison with full-face sections for a subset of the tumours, RBM3 did not seem to display a heterogeneous expression pattern." (PMID 21777469, 2011). "Interestingly, and in line with previous in vitro data, RBM3 expression was strong in the majority of primary tumours, but weak or absent in the metastases." (PMID 21777469, 2011). "This discrepancy may be due to the use of different IHC assessment strategies, limited follow-up data as well as the larger proportion of advanced tumours in the latter study, as the prognostic value of RBM3 was found to be more evident in non-muscle-invasive tumours." (PMID 35109796, 2022). "Furthermore, the patients with high tumor-specific RBM3 expression who did not receive chemotherapy may not have been fit enough to be given chemotherapy, thus having a worse prognosis regardless." (PMID 29464064, 2018).
tumor (continued). "In the LINC00096/miR-383-5p/RBM3 axis, lncRNA LINC00096 was upregulated in the triple-negative BC (TNBC) tissues, which was correlated with tumor stage, invasion, and the unfavorable prognosis of patients." (PMID 36313570, 2022). "The independent beneficial prognostic value of RBM3 expression for both RFS and OS was retained when subset analysis of tumours of pure ovarian origin (n = 243) was performed (data not shown)." (PMID 20727170, 2010). "A robust correlation between SF3B1 expression and the most critical oncogenic spliceosome components [SRSF3/RBM22/PTPB1/RBM3] was also found in GBM (CGGA- and Rembrandt-datasets), but not in the non-tumor samples (with the exception of PTBP1; Rembrandt-datasets)." (PMID 35086552, 2022). "Although the role of other members of the RBM proteins family in tumor treatment and prognosis is not clear, existing studies have shown that some members of RBM proteins family, such as RBM3, RBM4, and RBM39, play an essential role in tumor treatment and prognostic markers." (PMID 34804951, 2021). "Non-classic tumour types were significantly correlated with a more advanced higher T-stage (p < 0.001), grade (p < 0.001), membranous PODXL expression (p < 0.001) and low RBM3 expression (p < 0.001)." (PMID 28293425, 2017).
cancer (42 papers, 2010 to 2026). A tumor composed of atypical neoplastic, often pleomorphic cells that invade other tissues. "Previous studies have associated high RBM3 expression with an increased sensitivity to chemotherapy in other cancer types." (PMID 40506997, 2025). "Of note, contrasting associations of RBM3 expression with clinical outcome have been shown in particularly aggressive cancers such as pancreatic cancer." (PMID 35169225, 2022). "Upregulation has been demonstrated in various cancers, and in addition to its importance in cell cycle progression and anti‐apoptotic functions, RBM3 has been linked to increased stem cell characteristics." (PMID 32491279, 2020). "High RBM3 expression was associated with small, low-grade, ER-positive cancers, and improvement in recurrence free survival." (PMID 28118608, 2017). "Different expression levels of RBM3 have a significant connection to patient survival in various cancers, tremendous efforts have focused on studying the diagnostic and prognostic value of RBM3." (PMID 28118608, 2017). "Then, the roles of RBM3 in cancers and neuroprotection as well as the underlying mechanisms are discussed." (PMID 28118608, 2017). "As a glycine rich protein, high expression of RBM3 has been found to be associated with good prognosis in several types of cancers, including CRC18." (PMID 26013439, 2015). "Another way to reconcile RBM3’s effects on migration and its association with better cancer outcomes may be the subcellular distribution of RBM3." (PMID 29743635, 2018). "Therefore, it would be of interest to study the association of RBM3 with cisplatin sensitivity in this type of cancer." (PMID 28293425, 2017). "Pharmacological upregulation of RBM3 might be of broad utility in amplifying endogenous stress response mechanisms linked to cellular protection and repair in many tissues, and present a new strategy to regulating the metastatic behavior of many cancers." (PMID 29743635, 2018). "Furthermore, silencing of RBM3 led to reduced cancer cell migration and invasion, which reflects the findings of high RBM3 expression being associated with unfavorable clinicopathological characteristics, in particular in PB-type tumors, displaying the highest levels of RBM3 expression." (PMID 29464064, 2018). "Furthermore, low RBM3 expression in other cancer types is associated with poor survival as well." (PMID 27147467, 2016). "High expression of RBM3 may signify a subset of upper gastrointestinal cancers arising in a background of intestinal metaplasia and independently predicts a reduced risk of recurrence and death in patients with these cancer forms." (PMID 24963396, 2014). "Considered as a proto-oncogene, RBM3 dysregulation is found in a variety of cancers, including CRC, esophageal, urethral, prostate, melanoma, and others." (PMID 41516083, 2025). "RBM3, a well-proven oncoprotein in a variety of cancers, promotes the proliferation of HCC cells by increasing YAP1 expression." (PMID 37301543, 2023). "Some RNPs such as RBM3, IMP3, and CUG-BP1 facilitate the formation of drug resistance 22 while heterogeneous nuclear ribonucleoprotein K has been associated with cancer procession and high risk of metastasis." (PMID 37324186, 2023). "We have previously found that the mRNA level of RBM3 was decreased in metastatic PCa compared with organ-confined cancer, and that protein expression of RBM3 was also decreased in metastatic PCa." (PMID 36750551, 2023). "It is reported that RBM3 plays diverse physiological and pathological roles in inflammation, neural plasticity, stem cell properties, and cancer development." (PMID 37268694, 2023). "In the present study, we observed the colocalization of RBM3 protein with the mRNA of CTNNB1 when cancer cells were co-cultured with osteoblast cells to mimic a bone microenvironment." (PMID 36750551, 2023).